INS (insulin)
Diseases named in the same sentence as INS in open-access papers (continued):
Sharing a sentence is not in itself a finding about the gene and the disease.
Insulin resistance (continued). "Our findings suggest that an intact microtubule network is required for KIF5B-mediated intracellular GLUT4 movement and maintaining insulin-responsive glucose uptake, and that impaired microtubule-based GLUT4 trafficking is a feature of skeletal muscle insulin resistance." (PMID 37073948, 2023). "Measures of estimated beta-cell function were assessed in six studies including C-peptide levels and homoeostasis model assessment-2 indices for beta-cell function (HOMA2-B) or insulin resistance (HOMA2-IR), which require measurement of fasting insulin and glucose levels." (PMID 37798471, 2023). "Hyperglycemia develops when insulin secretion can no longer compensate for insulin resistance, originating a detrimental loop of insensitivity and dysfunction of the β cells." (PMID 36670995, 2023). "Namely, most of the studies reported an inverse relationship of birth weight with: i) fasting glucose and insulin levels; ii) glucose levels two hours after a glucose tolerance test; iii) prevalence of T2D; and iv) insulin resistance, regardless of sex." (PMID 37342257, 2023). "Obesity can lead to insulin resistance and affect insulin secretion and utilization As obesity progresses, fatty tissue begins to secrete hormones such as tumor necrosis factor-alpha (TNF-α) and interleukin-6 (IL-6), which exacerbate insulin resistance." (PMID 37740187, 2023). "Reductions in the number of insulin-secreting β-cells in pancreatic islets with the simultaneous expansion of glucagon-secreting α-cells as well as insulin hypersecretion in the absence of insulin resistance often precede the onset of type 2 diabetes." (PMID 37274331, 2023). "T2D is characterized by a relative lack of insulin secretion or insulin resistance occurring in the insulin-responding organs." (PMID 36904097, 2023). "Given the insulin resistance phenotypes in both WD and WD + STZ mice, this observation may be correlated with the presence of insulin-resistant peripheral tissues in which fatty acids become a favored energy source." (PMID 37885804, 2023). "In the case of insulin resistance, insulin fails to inhibit postprandial hepatic gluconeogenesis, resulting in an increase in blood glucose." (PMID 36452137, 2022). "Treatment with either MA ethanolic extract or pioglitazone was successful in ameliorating insulin resistance, hyperlipidemia, and fatty liver without having a significant effect on fasting insulin levels or pancreatic secretory capacity." (PMID 36160451, 2022). "Insulin resistance occurs when cells do not respond properly to insulin secreted by the pancreas, insulin no longer stimulates glucose uptake and utilization in muscle tissue, resulting in excess glucose in the blood." (PMID 36490255, 2022). "Metabolic syndrome and insulin resistance in obesity are characterized by an overexpression of insulin receptors, while insulin-related substrate (IRS), insulin, and IGFs are well-known influential factors for cell proliferation, differentiation, and regulation of the cell metabolism." (PMID 35276833, 2022). "Therefore, in this study, we determined the insulin resistance in PCOS rats, the results showed higher levels of glucose and insulin in PCOS rats, and HOMA-IR also increased." (PMID 36742000, 2022). "Furthermore, in post-intervention, we observed trends between Il-6 and insulin resistance measured by HOMA-IR (r = 26, p = 0.07), and Il-6 and plasma insulin values at 120 min during OGTT (r = 0.24, p = 0.10)." (PMID 35323474, 2022). "Nevertheless, excessive SELENOP may lead to insulin resistance, and treatment with the full-length form of SELENOP may impair insulin signal transduction in cultured hepatocytes." (PMID 35883754, 2022). "In subjects with obesity and/or metabolic syndrome, insulin resistance develops mainly due to overeating and/or lack of exercise, but sufficient insulin is secreted from intact β-cells to compensate for the insulin resistance." (PMID 35453568, 2022).
Insulin resistance (continued). "The lesser sensitivity or complete nonresponsivity of cells to insulin is termed insulin resistance, a typical symptom at the early stage of T2DM." (PMID 36699697, 2022). "Resveratrol administration effectively reduced serum insulin levels and improved insulin resistance (determined by the HOMA-IR index), but no changes in microbiota composition were observed." (PMID 36687699, 2022). "The fasting insulin-to-glucose ratio, an index of insulin resistance, was slightly but not significantly increased by both naringenin and 8-PN compared to that in the STZ control group." (PMID 35807469, 2022). "Insulin predominantly modulates postprandial glucose, and anomalies in the signal transduction pathway in skeletal muscle and adipose tissue, such as decreased GLUT4 translocation, are a major contributor to insulin resistance." (PMID 36005629, 2022). "In addition, the PCOS group had elevated fasting insulin levels, Homeostatic Model Assessment for Insulin Resistance (HOMA-IR), and lower sex hormone-binding globulin (SHBG) and Matsuda index levels (to measure insulin sensitivity) than controls (p ≤ 0.04)." (PMID 35628399, 2022). "In summary, in patients without a DM history, the higher insulin resistance, the lower the insulin sensitivity, the higher the T stage." (PMID 35299970, 2022). "Current efforts to treat T2DM and prevent its complications mainly focus on improving insulin sensitivity, enhancing insulin secretion, or supplementing exogenous insulin based on a common assumption that insulin resistance is noncommunicable." (PMID 36699697, 2022). "Therefore, irisin can improve insulin resistance via the signaling pathways of PI3K/Akt and p38MAPK and enhance the AD brain’s glucose metabolism and the role of insulin." (PMID 36203845, 2022). "The primary endpoint was insulin resistance index (IRI), and the secondary endpoints were fasting blood glucose, fasting insulin, insulin secretion index, insulin sensitivity index, intraoperative blood glucose, subjective comfort score, and clinical outcome indicators." (PMID 35718790, 2022). "Using this multi-factorial approach, we find clear evidence that Insr signaling plays a suppressive role on insulin secretion by modulating β-cell electrical excitability and that this effect is absent in conditions of global insulin resistance." (PMID 35136059, 2022). "When mice were propagated on C57BL/6J, they displayed primarily insulin resistance without significant effect on insulin clearance." (PMID 36009446, 2022). "Insulin resistance can be assessed with different methods, such as an insulin maximal blood level above 50 μU/mL within 90 min after 75 g of glucose load (OGTT), insulin basal plasma level above 12 μU/mL, or a glucose-to-insulin ratio <4.5." (PMID 36009471, 2022). "In this regard, some studies have attributed the reduction in insulin clearance rate in obese subjects to insulin resistance rather than to excessive adiposity." (PMID 36009446, 2022). "Furthermore, insulin resistance was improved and the phosphorylation of hypothalamic PI3K/Akt/mTOR proteins involved in insulin signaling was up-regulated." (PMID 36246070, 2022). "Also, insulin resistance assessed by HOMA-IR was significantly reduced in the 2′-FL group, suggesting improved insulin action in livers of 2′-FL fed mice." (PMID 35782914, 2022). "Insulin resistance, understood as a target organ’s reduced sensitivity to insulin, results in hyperinsulinemia but not in high insulin concentrations in the CSF, where the insulin concentrations are reduced." (PMID 35615716, 2022). "In healthy, non-obese, Japanese men, low insulin clearance rate is thought to be an early adaptation to maintain normal metabolism and counter adiposity-driven modest impairment of insulin resistance in skeletal muscle." (PMID 36009446, 2022). "This previous meta-analysis indicated that folate does not influence FPG, but improves insulin resistance by decreasing insulin levels." (PMID 35215533, 2022).
Insulin resistance (continued). "Additionally, STL exhibited the potential to stimulate glucose uptake and attenuate insulin resistance, presumably by modulation of expression of GLUT-4 and RSTN genes in insulin-resistant adipocytes." (PMID 36297315, 2022). "Supplement of MET to lifestyle intervention has no additional effect on insulin sensitivity in PCOS, which infers that weight loss is the main mechanism for decreased insulin resistance during MET." (PMID 36557221, 2022). "Consequently, increased β-amyloid levels antagonize insulin and IGF-1 receptor binding, which results in the secretion of inflammatory agents and the onset of insulin resistance." (PMID 35269827, 2022). "However, it was negatively correlated with BMI,fasting insulin, insulin 1–3 h postprandial, lymphocyte count, HOMA insulin resistance index and estimated glomerular filtration rate." (PMID 35443645, 2022). "Insulin resistance occurs due to degradation and downregulation of insulin receptor substrate (IRS), alterations in insulin signaling pathways, induction of viral hepatic steatosis, and increase in reactive oxygen species and inflammatory cytokines causing peripheral and hepatic insulin resistance." (PMID 36168334, 2022). "Furthermore, glucose and insulin tolerance tests (GTT and ITT, respectively) revealed that Mat2a deletion protected against HFD-induced glucose intolerance and insulin resistance." (PMID 35729157, 2022). "As LPL is activated by insulin also in BAT, and LPL activation is compromised by insulin resistance, reduced LPL levels in cold-housed Cyp7b1−/− mice might result from their insulin resistance." (PMID 35478959, 2022). "With a high fat/caloric diet this technique produces insulin resistance and glucose intolerance without insulin dependency; suggestive of a T2DM model." (PMID 36389223, 2022). "Moreover, these rats were prediabetic since they have significantly elevated plasma insulin levels, HOMA-IR, and insulin resistance." (PMID 35119333, 2022). "Moreover, insulin resistance, hepatitis C, pancreatic cancer, TNF signaling pathway, insulin signaling pathway, and PI3K-AKT signaling pathway were the mechanisms by which apple pollen exerted its therapeutic effect on T2DM." (PMID 35656465, 2022). "Additionally, the elevation of glucose and insulin levels was prevented by RB supplementation in animals fed HSF since the values were similar to C group, as well as the insulin resistance, assessed by HOMA-IR, a marker of metabolic homeostasis." (PMID 34636986, 2022). "Acquired insulin resistance in skeletal muscles, liver, and adipose tissue may contribute to the promotion of LADA by increasing the demand on the beta-cells to increase insulin production." (PMID 35846274, 2022). "Additionally, some studies also discussed the correlation between insulin resistance and PCOS, and some reported that insulin sensitivity increased after the MSC treatment." (PMID 36662487, 2022). "In recent years, other standards for measuring insulin sensitivity have been developed, such as the homeostasis model assessment-insulin resistance (HOMA-IR), quantitative insulin sensitivity check index (QUICKI), and triglyceride to high-density lipoprotein cholesterol (TG/HDL-C) ratio tools." (PMID 35778731, 2022). "Here, we demonstrate our non-obese mouse model displays insulin resistance and impaired insulin secretion defects making it an ideal model for studying the pathophysiology of GDM." (PMID 36520818, 2022). "Specifically, it would be useful to incorporate measures of insulin resistance that are derived from fasting or post-glucose load glucose and insulin values rather than relying exclusively on adipokine values." (PMID 35662920, 2022). "miR-222-3p was positively-correlated with fasting plasma glucose (FPG), fasting insulin (FINS), homeostatic model assessment–insulin resistance (HOMA-IR), and low-density lipoprotein cholesterol (LDL-C) and negatively-correlated with high-density lipoprotein cholesterol (HDL-C)." (PMID 36182923, 2022).
Insulin resistance (continued). "BMI = body mass index; DBP = diastolic blood pressure; FPG = fasting plasma glucose; FPI = fasting plasma insulin; TGL = fasting serum triglycerides; HbA1c = glycated hemoglobin; HOMA-IR = homeostatic model assessment for insulin resistance; SBP = systolic blood pressure." (PMID 35770520, 2022). "Therefore, compared with young rats, the serum insulin concentration of aged rats must be lower, so the HOMA-IR formula cannot fully reflect the degree of insulin resistance in young and old rats." (PMID 35811955, 2022). "Another primary reason for insulin resistance is an altered serine/threonine phosphorylation of IRS-1 by a large number of protein kinases, a critical event explaining the molecular basis of the down-regulation of insulin signaling." (PMID 36547071, 2022). "From a medical point of view, it is a chronic noncommunicable disease arising from impaired insulin secretion and insulin resistance, leading to its defining feature of hyperglycemia." (PMID 35807588, 2022). "Although increased O-GlcNAcylation can compromise insulin sensitivity via effects on mediators of insulin signaling, this is clearly not the primary mechanism for insulin resistance in type 2 diabetics or hyperglycemia in type 1 diabetics." (PMID 36135209, 2022). "Patients in subgroup B were older, without severe impaired insulin secretion, severe insulin resistance or obesity." (PMID 35948978, 2022). "The second aim of this study was to investigate the associations between DII and the markers of T2D risk, namely, fasting plasma glucose [FPG], glycohemoglobin [HbA1c], fasting serum insulin [FSI], and homeostatic model assessment of insulin resistance index [HOMA-IR]." (PMID 35250879, 2022). "Insulin resistance is a complex condition in which the body does not respond adequately to insulin, a hormone secreted by the pancreas with an essential role in the regulation of blood sugar levels [...]." (PMID 36145093, 2022). "In this study, we found that the differences between subjects with and without central obesity were mainly in weight, WC, insulin level and insulin resistance in both ethnic groups and in both the prediabetes and T2DM populations." (PMID 35325446, 2022). "Fasting insulin and HOMA-IR are indicators of insulin resistance." (PMID 35232402, 2022). "METS-IR is insulin-independent and studies have shown that it is superior to other non-insulin-based indicators of insulin resistance and has the advantage of being stable and reproducible." (PMID 36211651, 2022). "This study was aimed at assessing serum fasting insulin levels, the homeostatic model assessment for insulin resistance (HOMA-IR), and serum lipid levels in non-obese patients with primary hypertension when compared to normotensive subjects." (PMID 35482462, 2022). "Increased adiposity per se, not insulin resistance, enhanced insulin secretion in people with obesity." (PMID 34905513, 2022). "Homeostasis model assessment for insulin resistance (HOMA-IR) was first introduced by Turner of the University of Oxford research group in 1985, which provides an estimate of IR based on fasting glucose and insulin levels." (PMID 36002887, 2022). "Nevertheless, the authors also revealed that CMPF was not a significant determinant of the postpartum whole-body insulin sensitivity index (Matsuda index) or homeostatic model assessment for insulin resistance (HOMA-IR)." (PMID 35457182, 2022). "Moreover, insulin resistance was validated in the present study using QUICKI, which revealed significant reduction in insulin sensitivity." (PMID 35881588, 2022). "Importantly, overexpression of RBP4 in mice or its administration elicited insulin resistance and diminished glucose tolerance, whereas RBP4 knockout mice showed improved insulin sensitivity." (PMID 35334893, 2022).
Insulin resistance (continued). "UA can also inhibit the trigger of insulin signaling at receptor level through an ectonucleotide pyrophosphatase / phosphodiesterase 1 (ENPP1) recruitment, and induce insulin resistance by NOD-like receptor family pyrin domain containing 3(NLRP3) inflammasome activation." (PMID 36464722, 2022). "In addition, the treatment caused a reduction of fasting glycemia and insulinemia, improved glucose (IPGTT) and insulin (ITT) tolerance tests, and restored HOMA index (a marker of insulin resistance)." (PMID 36552572, 2022). "Insulin resistance leads to inappropriate release of fatty acids through dysregulated lipolysis, which further leads to impaired systemic insulin signaling, suggesting that HFD-induced lipotoxicity had a greater effect on insulin signaling than sucrose." (PMID 35928832, 2022). "Pathophysiology of T2D is characterized by predominant insulin resistance than impaired insulin secretion in Caucasians whereas impaired insulin secretion rather than insulin resistance predominates in Asians." (PMID 36267570, 2022). "Lean PCOS patients, also inside the A and B phenotypes, had normal insulin circulating levels, no clinically relevant insulin resistance, and normal lipid profile." (PMID 36292002, 2022). "Insulin resistance is seen when liver, fat, and muscles do not respond well to endogenously secreted insulin and are unable to effectively take up glucose from blood." (PMID 35883660, 2022). "In the DIPD group, the elevated plasma insulin, impaired fasting glucose and HOMA-IR value in the range of insulin resistance may suggest that there is some insulin resistance from peripheral tissue against the uptake of glucose." (PMID 35898447, 2022). "The disease is classified into two predominant types: type 1 DM, characterized by the absence of endogenous insulin, and type 2 DM, marked by insulin resistance." (PMID 36340870, 2022). "Therefore, future work must consider pre-pregnancy and pregnancy parameters, including maternal BMI/adiposity, hyperglycaemia, insulin resistance, and insulin sensitivity, as confounding factors in the relationship between GDM and HM insulin." (PMID 36079876, 2022). "As expected, both forms of overweight/obesity displayed decreased in vivo insulin sensitivity, but the level of insulin resistance was not different between EOO and LOO." (PMID 35228658, 2022). "Our data indicate that the insulin secretory response to plasma glucose was already at its maximum in individuals who are obese and insulin sensitive, and did not increase further with increasing insulin resistance." (PMID 34905513, 2022). "Circulating betatrophin/ANGPTL8 was detectable in 66 subjects (sepsis: n = 16; insulin resistance: n = 32; no insulin resistance/no systemic inflammation: n = 18)." (PMID 36551906, 2022). "In contrast to the improved insulin sensitivity caused by MT1-MMP depletion, ectopic MT1-MMP expression in the liver induces insulin resistance, despite no changes in body weight and composition." (PMID 35768470, 2022). "These mice did not experience glucose intolerance nor insulin resistance, but their islets had reduced insulin and increased glucagon." (PMID 35458115, 2022). "Insulin resistance (IR) is a physiological abnormality that occurs when insulin fails to activate the signal transduction pathway in target organs." (PMID 36082026, 2022). "Mechanistically, the pro-proliferative and anti-apoptotic effect of insulin and IGF on endometrial cells, induced by insulin resistance in T2DM may be expected to lead to more aggressive endometrial cancer phenotypes." (PMID 35600348, 2022). "It has been shown that removing M1‐like macrophages from obese mice can restore insulin sensitivity without affecting body weight, suggesting that M1‐like macrophage‐induced insulin resistance is independent of body weight." (PMID 35258174, 2022).